BRD4 (bromodomain containing 4)
Diseases named in the same sentence as BRD4 in open-access papers (continued):
Sharing a sentence is not in itself a finding about the gene and the disease.
neuroblastoma (41 papers, 2014 to 2025). Neuroblastoma (NB) is the most common solid, extracranial childhood tumor. "Studies have confirmed that the circRNA derived from Cux1, encoding protein P113, drives neuroblastoma (NB) progression by facilitating the trans-activation of ZRF1/BRD4." (PMID 39103807, 2024). "One of the prominent members of BET proteins, Brd4, has been implicated in multiple cancers including neuroblastoma, oral, breast, lung, and colon malignancies through ET-mediated protein–protein interactions." (PMID 37049806, 2023). "CDK7 phosphorylates serine 5 of Pol2 at the promoter to promote initiation, and it has been shown that CDK7 inhibitors have a synergistic effect when combined with BRD4 inhibitors in neuroblastoma, so a local increase in CDK7 could also be implicated." (PMID 37259348, 2023). "Supporting this possibility, previous studies have shown that BRD4 inhibition reduces MYCN expression in neuroblastoma cells." (PMID 40867243, 2025). "Another BET inhibitor, OTX015, is effective against mouse and human MYCN-driven neuroblastoma in models, as it can selectively disrupt the binding of BRD4 and SEs and lead to the repression of MYCN expression." (PMID 36720920, 2023). "For example, interactions between JMJD6 and the Brd4 ET domain are known to drive the progression of neuroblastoma, oral, breast, lung, prostate, and colon cancers." (PMID 37049806, 2023). "Combination therapy with JQ1 and the novel CDK7 inhibitor YKL-5-124 shows a synergistic effect in neuroblastoma and can delay resistance to BRD4 inhibition." (PMID 36720920, 2023). "This research focused on identifying potentially natural compounds that would be more patient-friendly, due to having fewer toxic effects and side effects, for treating MYCN overexpressing neuroblastoma patients by targeting the Brd4 protein." (PMID 36286044, 2022). "This identification of potential lead natural compounds would be able to inhibit the Brd4 protein in neuroblastoma treatment by silencing the expression of MYCN." (PMID 36286044, 2022). "Here, we summarized and reviewed the recent research progresses for the critical function of BET proteins, as an epigenetic reader, on tumorigenesis and the therapeutic potential of the BET/BRD4 inhibitors on MYCN amplified neuroblastoma." (PMID 36187481, 2022). "Like CBP and its CREB and p300 co-factors, BRD4 expression level is predictive of neuroblastoma patient outcome." (PMID 33968920, 2021). "First, to confirm the effects of BRD4 inhibition in neuroblastoma cells, a dose course of the BRD4 inhibitors JQ1 and I-BET were assessed in the cell line panel." (PMID 33968920, 2021). "Of the four members of the BET family proteins, BRD4 is the most thoroughly characterized, and its aberrant activity has been associated with NUT midline carcinoma, colon, breast and prostate cancers, neuroblastoma, and hematopoietic cancers." (PMID 32694708, 2020). "Our results also implicate that the pharmacologic inhibition of BRD4 by ARV-825 caused a reduction in MYCN or c-Myc mRNA and protein expression in neuroblastoma." (PMID 33324552, 2020). "Our studies have shown that PTEN/PI3K signaling axis in macrophages promotes tumor metastasis and use of dual PI3K/BRD4 inhibitors SF1126 or SF2523 blocked tumor metastasis in neuroblastoma mouse model." (PMID 32983125, 2020). "Combinations of CDK7i with other cancer therapeutics have also been explored, for example, BRD4 and CDK7i have been shown to work synergistically in neuroblastoma and a combination of PARP and CDK7i show synergism for the treatment of Ewing Sarcoma." (PMID 31530935, 2020). "Immunoblot analysis showed that the anti-BRD4 and anti-JMJD6 antibodies efficiently immunoprecipitated both BRD4 and JMJD6 proteins, suggesting that JMJD6 forms a protein complex with BRD4 in neuroblastoma cells." (PMID 31346162, 2019). "Neuroblastoma cell lines were treated with the combination of the BRD4 inhibitor, JQ1, and theCDK7 inhibitor, THZ1." (PMID 30326621, 2018).
neuroblastoma (continued). "SF1126 inhibits BRD4 bromodomain binding to acetylated lysine residues with histone H3 as well as PI3K activity in the MYCN amplified neuroblastoma cell line IMR-32." (PMID 28881723, 2017). "Our results revealed differentially activated epigenetic regulators, including HDACs and BRD4, thus confirming the recently identified role for HDACs in neuroblastoma responsiveness to RA." (PMID 28187790, 2017). "In the present study we found that SF1126 displaces BRD4 from MYC transcriptional start site in IMR-32 neuroblastoma cell line." (PMID 28881723, 2017). "All the cell lines tested expressed BRD2, BRD3 and BRD4 at least two times more than normal mesenchymal stem cells (MSCs), except the SK-N-MC cells, potentially because of their neuroblastoma origin." (PMID 27006472, 2016). "Several hematologic malignancies, the highly malignant NUT midline carcinoma and the pediatric adrenal gland tumor neuroblastoma are responsive to BRD4 inhibition in vitro and in mouse models." (PMID 24796395, 2014). "BRD4 ("Bromodomain-containing protein 4"), a recognized gene regulator, is an attractive target for therapeutic development, particularly for the management of neuroblastoma." (PMID 41125627, 2025). "We find it interesting that the supermediator activity of NonO may function in neuroblastoma via its interaction and coregulation of BRD4/Bromodomain, which retards neuroblastoma growth via apoptosis." (PMID 38248868, 2024). "In neuroblastoma, the most common solid tumor of the neural crest cell origin in children, dBET57 was recently shown to target Brd4 ubiquitination, inhibit the super-enhancer-related genes ZMYND8 and TBX3, and exhibit a potent anticancer effect both in vitro and in vivo." (PMID 37049806, 2023). "JQ1, the first developed BET inhibitor, could efficiently suppress the expression of MYCN in neuroblastoma by inhibiting the binding of BRD4 with acetyl lysine of histone." (PMID 36187481, 2022). "Therefore, the study aimed to identify potential inhibitors against the BET family protein, specifically Brd4 (brodamine-containing protein 4), to hinder the activity of neuroblastoma cells." (PMID 36286044, 2022). "Although our results showed that BRD4 expresses universally in neuroblastoma cells as well as a variety of other types of tumors, high expression of BRD4 was closely related to poor prognostic outcome in neuroblastoma, suggesting BRD4 can potentially serve as a prognostic marker in neuroblastoma." (PMID 33324552, 2020). "The protein level of BRD4 was compared between neuroblastoma and peripheral neurons." (PMID 33324552, 2020). "Notably, it was previously shown that transcription of MYCN in MYCN amplified neuroblastoma cells relies on BRD4 expression and that BRD4 inhibition by BET-bromodomain inhibitors decreases MYCN expression." (PMID 31414211, 2019). "The aim of this study was to evaluate the role of PTEN/PI-3K and the BRD4/MYCN signaling axis and a “first in class” dual PI-3K/BRD4 inhibitor, SF1126 as biomarkers and a therapeutic strategy, respectively for the treatment of MYCN dependent high risk neuroblastoma." (PMID 28881723, 2017). "Since single agent treatments have thus far not provided the desired outcome benefit for high-risk neuroblastoma patients and since they can lead to acquired drug resistance, we also assessed the utility of a BRD4 inhibitor (JQ1) and CBP/p300 inhibitor (C646 and I-CBP112) combination." (PMID 33968920, 2021). "Additionally, this strategy may prevent the emergence of resistance to BRD4 inhibitors, which are currently being tested in Phase 1 trials in pediatric patients with solid tumors, including neuroblastoma." (PMID 35198433, 2021). "Importantly, we have confirmed that JMJD6 protein forms a complex with BRD4 protein in neuroblastoma cells, that JMJD6 protein directly binds to N-Myc protein at the Myc Box II region, and that the majority of super-enhancers, typical enhancers, and promoters bound by JMJD6 are also bound by N-Myc." (PMID 31346162, 2019).
neuroblastoma (continued). "ARV-825, a BRD4 PROTAC, exhibits significant antitumor activity in various models (neuroblastoma, thyroid cancer, and T-ALL) by degrading the BRD4 protein and suppressing MYC expression, thereby inhibiting tumor cell proliferation." (PMID 40507967, 2025). "Combined PI3K and BRD4 inhibition also shows promise, suppressing MYCN expression and inhibiting neuroblastoma cell growth and metastasis both in vitro and in vivo." (PMID 38087370, 2023). "In neuroblastoma due to TERT gene rearrangement with super-enhancers, BRD4 is required for TERT gene transcription and neuroblastoma cell proliferation." (PMID 38135679, 2023). "BET bromodomain inhibitors like JQ1 and I-BET726 displace BRD4 from the MYCN promoter, leading to improved survival in various in vivo neuroblastoma models by inhibiting tumor growth and MYCN downregulation." (PMID 38087370, 2023). "It precisely targets BRD4 proteins, induces the degradation of BRD2 and BRD3, and has a strong antitumor effect on neuroblastoma." (PMID 36438198, 2022). "Three different PROTAC BRD4 inhibitors (MZ1, dBET1, GNE-98) were used to evaluate their efficacy in neuroblastoma cells." (PMID 33324552, 2020). "BET inhibitors, such as JQ1 and OTX015, can displace the BRD4 oncoprotein from chromatin, which potently represses MYCN transcription in neuroblastoma cell lines and effectively reduces neuroblastoma cell viability in vitro and in vivo." (PMID 33614505, 2020). "BRD4 and CDK7 inhibitors synergistically repress the expression of all the CRC transcription factors and N-MYC, which inhibits neuroblastoma cell growth." (PMID 33614505, 2020). "Altogether, these data from 4 different BRD4 PROTAC inhibitors indicate that PROTAC BRD4 inhibitors suppress MYCN or c-Myc expression by BET proteins depletion, thus inhibiting cell proliferation and inducing apoptosis in neuroblastoma cells." (PMID 33324552, 2020). "BRD4 inhibitors are known to inhibit transcription of MYCN, induce apoptosis and impair tumor growth of neuroblastoma." (PMID 32722460, 2020). "The pre-clinical studies carried out in our lab have shown that dual PI3K/BRD4 inhibitors SF1126 and SF2523 suppress neuroblastoma tumor growth, angiogenesis and metastasis." (PMID 32722460, 2020). "In an effort to support the progression of BRD4 inhibitors to the pediatric clinic for neuroblastoma, OTX015, an orally-administered compound, was studied in a panel of preclinical neuroblastoma models." (PMID 35582571, 2019). "The effects of combined BRD4 and CDK7 inhibition on both CRC and global gene expression were evaluated in neuroblastoma cell lines." (PMID 30326621, 2018). "We also determined the effect of manipulation of the PTEN/PI3K/AKT signaling pathway on growth of neuroblastoma xenografts in vivo and in vitro by treatment with an RGD-targeted dual PI3K/BRD4 inhibitor, with anti-tumor and anti-angiogenic activity, SF1126." (PMID 28881723, 2017). "Mechanistically, the quinone-containing compound nanaomycin induced neuroblastoma cell death but also activated the Nrf2-antioxidant signaling pathway, and the BET bromodomain proteins BRD3 and BRD4 formed a protein complex with Nrf2." (PMID 27764794, 2016). "Moreover, the combined application of BRD4 inhibitor I-BET151 and AURKA inhibitor alisertib significantly inhibited the neuroblastoma cells growth and dramatically prolonged the survival time of neuroblastoma xenograft mice." (PMID 36187481, 2022). "The combination of CDK7 and BRD4 inhibition provides a therapeutic option for neuroblastoma and suggests that the addition of YKL-5-124 could improve the therapeutic efficacy of JQ1 and delay resistance to BRD4 inhibition." (PMID 35198433, 2021). "The use of dual PI3K/BRD4 inhibitors SF1126 or SF2523 blocks tumor growth, angiogenesis, stabilization of HIF1/2α, and polarization of M2 macrophages in solid tumors including neuroblastoma." (PMID 32983125, 2020).
neuroblastoma (continued). "We have recently shown that BRD4 promotes polarization of macrophages into anti-inflammatory phenotype and treatment with bromodomain inhibitor JQ1 or dual PI3K/BRD4 inhibitor SF1126 or SF2523 blocks immunosuppression and promotes adaptive immune responses in solid tumors including neuroblastoma." (PMID 32983125, 2020). "In addition, targeting BRD4 by BET inhibitor displaces BRD4 from the MYCN promoter region and downregulates MYCN expression in neuroblastoma cells, establishing BRD4 as a transcriptional regulator of MYCN." (PMID 33324552, 2020). "Based on this, it was hypothesized that disrupting the CRC and transcriptional initiation and elongation through BRD4 and CDK7 inhibition may be an effective strategy for treating neuroblastoma." (PMID 30326621, 2018). "Finally we showed that the integrin-targeted dual pan- PI3K/BRD4 inhibitor, SF1126, potently blocked tumor growth and tumor angiogenesis along with decreasing MYCN mRNA and protein in subcutaneous neuroblastoma xenografts." (PMID 28881723, 2017). "Our data suggest that neuroblastoma cells co-treated with JQ1 and anti-microtubule drugs are unable to recover from anti-microtubule drug-mediated cell cycle arrest at the mitotic phase due to JQ1-induced BRD4 inhibition." (PMID 27764794, 2016). "We examined the chromatin marks at the TERT locus and found that neuroblastoma cells with MYCN amplification and short telomeres are enriched for chromatin marks indicative of open chromatin including H3K4me3, H3K27Ac, H3K14Ac, RNA PolII, and BRD4 at the TERT promoter." (PMID 38837897, 2024). "While not investigated in neuroblastoma, PI3K/BRD4 blockade has demonstrated immunomodulatory effects." (PMID 38087370, 2023). "Indeed, pathological features can overlap between embryonal tumor subtypes, particularly those with BRD4::LEUTX fusions and FOXR2-activated neuroblastomas; most notably the small poorly differentiated cells, abundant necrosis, and co-expression of immunomarkers synaptophysin and OLIG2." (PMID 38500181, 2024).
pancreatic cancer (40 papers, 2015 to 2026). "At the chromatin level, BRD2 and BRD4 ChIP-seq analysis of pancreatic cancer cells showed consistent BRD4 loss from chromatin after JQ1 treatment, while BRD2 displacement differed by sensitivity." (PMID 42069518, 2026). "Clinical studies further indicated that in pancreatic cancer patients, BRD4 (high)/caveolin-2 (high) was associated with shorter disease-free survival." (PMID 37953273, 2023). "It has been demonstrated that higher expression of CAV-2 and its upstream regulator bromodomain containing 4 (BRD4) is associated with shorter overall survival of 76 pancreatic cancer patients." (PMID 34078402, 2021). "We found that TPL, cytotoxic to both pancreatic tumor cells and CAFs, disrupted SEs in a manner that resulted in the downregulation of SE-associated genes (e.g., BRD4, MYC, RNA Pol II, and Collagen 1) in both cell types at mRNA and protein levels." (PMID 33168807, 2020). "In the present review, we summarized the mutations of epigenetic regulators, including ARID1A, SMARCA2, SMARCA4, KDM6A, KMT2C, KMT2D, and BRD4 in GI cancers—in particular, pancreatic cancer—and found these regulators to be frequently mutated." (PMID 31238554, 2019). "Collectively, this study revealed that environmental damage, in combination with KRAS mutation, induces BRD4-dependent epigenetic reprogramming, as well as identified IL-33 as an effector of environmental damage to drive early-stage neoplasia for pancreatic cancer initiation." (PMID 34023857, 2021). "FBP1 downregulates the levels of the BRD4 target genes WNT5a, FLRT2, and PDE9A, and partially inhibits pancreatic cancer through BRD4 progression." (PMID 40100307, 2025). "We selected three important target genes (BTK, SYK and BRD4), and tested the anti-tumor effects of their inhibitors on pancreatic cancer cell lines." (PMID 40859234, 2025). "We and others have shown that small molecule inhibitors of BRD4 can reduce inflammation and disease progression in models of pancreatic cancer." (PMID 39337472, 2024). "In pancreatic cancer, it is found that cancer‐associated fibroblasts (CAFs) in the tumor microenvironment reduce the BET inhibitor JQ1 sensitivity by inducing BRD4 expression." (PMID 37968249, 2024). "For instance, in a study of pancreatic cancer, activation of the BRD4 gene in cancer cells causes NR5A2 to be transcribed and upregulated, thus promoting pancreatic cancer progression." (PMID 38358044, 2024). "Our previous research has indicated that CAFs promote proliferation and metastasis in pancreatic tumors, and they can also increase the expression of BRD4 in cancer cells, potentially leading to reduced sensitivity of pancreatic cancer cells to JQ1." (PMID 37968249, 2024). "Another study showed that suppression of BRD4 by JQ1 robustly blocked TGFBR2 level in pancreatic cancer cells." (PMID 37737256, 2023). "This preclinical study provides a mechanistic understanding of the benefit of combining TOP1 and BRD4 inhibitors to treat pancreatic carcinomas addicted to oncogenic drivers of transcription and replication." (PMID 37831776, 2023). "LINC00346 inhibits BRD4 expression to promote pancreatic cancer growth and gemcitabine resistance, primarily by sponging miR-188-3p." (PMID 35262384, 2022). "Elevated expression of BRD4 in pancreatic cancer has been attributed to presence of 5-hydroxymethylcytosine (5hmC) at the BRD4 promoter, indicative of an active DNA demethylation process (ADD)." (PMID 34996497, 2022). "For instance, we showed that FBP1 interacted with BRD4 to enhance pancreatic cancer cell sensitivity to BET inhibitors." (PMID 34854226, 2022). "Collectively, these data suggest that the ability of HAT1 to induce PVT1 expression in pancreatic cancer cells requires BRD4." (PMID 34564701, 2021). "Overall, our study suggests that BRD4/NR5A2/GDF15 axis is a promising therapeutic target in pancreatic cancer." (PMID 33850096, 2021).